MTOR (mechanistic target of rapamycin kinase)
Diseases named in the same sentence as MTOR in open-access papers (continued):
Sharing a sentence is not in itself a finding about the gene and the disease.
tumor (continued). "Previously, it was demonstrated that NPC tumor tissues had elevated PNCK expression, and it could regulate cell proliferation and apoptosis through the PI3K/AKT/mTOR signaling pathway." (PMID 35535310, 2022). "Further investigations indicated that compound decreased VEGF-induced phosphorylation of Akt, mTOR, MEK1/2, ERK1/2, and p38 MAPK in endothelial cells, and, by inhibiting Akt/mTOR and ERK-dependent pathways, it strongly suppressed tumor cell growth and proliferation." (PMID 36012142, 2022). "Based on these results, tumor spheroids derived from one of the four included patients (male, 24) diagnosed with GBM featuring ependymoma regions was found sensitive to JAK/STAT and mTOR inhibition." (PMID 35955765, 2022). "Coincidentally, high expression of miR-1265 is negatively related to tumor size in GC; moreover, it facilitates apoptosis but suppresses proliferation and autophagy by impairing the LKB1-STRAD-CAB39 complex and regulating the AMPK/mTOR signaling pathway." (PMID 36353541, 2022). "Among the more sensitive drugs in the high-risk group, phenformin had been shown to act as an authentic tumor disruptor, not only to maintain energy metabolism homeostasis by activating AMP-activated protein kinase (AMPK), but also as a blocker of mTOR regulatory complexes." (PMID 36355508, 2022). "This cluster reduces tumor growth by inhibiting proteins involved in important cellular processes, including homeobox A1 (HOXA1), mammalian target of rapamycin (mTOR), insulin-like growth factor binding protein 1 (IGFBP1), and fibroblast growth factor receptor 3 (FGFR3)." (PMID 35327452, 2022). "Among them, CLDN14 could promote tumor proliferation, and invasion through the PI3K/AKT/mTOR pathway." (PMID 36098705, 2022). "Furthermore, tumor-derived redHMGB1 was identified as the priming signal, which, through TLR4 and mTOR/AKT pathway, induced Bcl6-driven program underpinning SMMs generation." (PMID 36542153, 2022). "Similarly, a combination of mTOR kinase inhibitors with immune-checkpoint blockers such as anti-PD-1, anti-PD-L1, or anti-CTLA-4 significantly reduced MC38 or CT-26 tumor development." (PMID 36428613, 2022). "Subsequently, up-regulated PPARαδ inhibits mTOR-mediated glycolysis, impedes the generation of IFN-γ and cytotoxic granules, and prevents the recruitment of cytotoxic granules into the synapses between NK cells and tumor cells." (PMID 35062950, 2022). "Many data are now suggesting that these enzymes are critical for intima and adventitia neoplasia, EndoMt transition and reduction in inflammation; the intricacy of PI3K/AKT/mTOR signalling organization can suite the challenge for discovering new therapeutic uses of PI3K/AKT/mTOR inhibitors in AVF." (PMID 35327539, 2022). "In contrast, the phospho-AMPK and Akt/mTOR signaling pathways were activated in OR CRC cells, reducing tumor-suppressive autophagy, which protects these cells by increasing the levels of enzymes involved in glycolysis, especially GLUT1, PFKFB3 and PFK1, thereby maintaining resistance to oxaliplatin." (PMID 36359211, 2022). "Furthermore, there is evidence that enhanced inhibitory-receptor signals in T cells, such as CTLA-4 and PD-1, restrain glucose consumption and glycolytic capacity, leading to dampened mTOR activity and IFN-γ production, thereby allowing tumor progression." (PMID 35920986, 2022). "Not surprisingly, FDA approval of mTOR inhibitors, including everolimus and temsirolimus, is only limited to the control of late-stage tumor expansion in a few specific cancers." (PMID 36396656, 2022). "mTOR signaling plays critical roles in the tumor microenvironment (TME) and tumor angiogenesis." (PMID 36164611, 2022). "More importantly, CXCR4 directly controlled cell proliferation of non-hematopoietic cells and tumor cell growth and transduced signaling through mTOR pathway." (PMID 36163180, 2022).
tumor (continued). "TsIIA’s tumor suppressive effect, for example, is primarily dependent on the PI3K/AKT/mTOR signaling pathway and the JNK pathway, whereas CYT is more dependent on State3-mediated anti-tumor effects and has stronger immunomodulatory effects than the other three components." (PMID 36080361, 2022). "Pro-tumorigenic tumors displayed upregulation of genes related to pro-tumoral processes such as adhesion or migration (NCAM1), proliferation (CDK1, TOP2A) or extensively described tumor markers (CDKN2A, MTOR), among others, while showing an impairment in immune-related functions." (PMID 35329826, 2022). "Collectively our results suggested that EGFR, MAP2K1, mTOR, TEAD1, and YAP1 could mediate invasive tumor phenotypes and worsen prognoses via mechanisms involving both T-cell exclusion and dysfunctional phenotypes." (PMID 35655775, 2022). "Therefore, co-targeting PI3K, mTOR, and IGF1R proved to be effective in reducing tumor growth and decreasing cell migration and invasion." (PMID 35760832, 2022). "Combining mTOR inducer, MHY1485, with conventional chemoradiation could potentially result in a more effective treatment, in which CSCs and the bulk tumor cells are both targeted, leading to both an increased therapy response and a better long-term survival." (PMID 35406578, 2022). "Eugenol inhibits tumor migration and invasion by regulating the PI3K/Akt/mTOR pathway." (PMID 35847368, 2022). "We further used the myr-AKT plasmids to show that constitutive activation of AKT largely restored mTOR activation and subsequent Bcl6 expression even with no tumor instruction." (PMID 36542153, 2022). "On the other hand, CBX7-associated transcriptome profiles are significantly depleted with the targets for c-Myc or E2F transcription factors, as well as the markers of mTOR signaling or G2/M checkpoint, regardless of the tumor type." (PMID 36361869, 2022). "Importantly, pharmacological inhibition of mTOR or MEK lowered the abundance of PCNA, a marker of tumor cell proliferation, and subsequently suppressed ribosome biogenesis, cell growth and xenograft growth in mouse model." (PMID 35437691, 2022). "Combined regulatory activity, not necessarily monoactivity in tumor tissues is required, as exemplified for mTOR inhibitors, α-interferon, chemotherapy, PPARα/γ agonists." (PMID 35814409, 2022). "The fourth patient experienced stable disease and absence of tumor growth while on the combination of trametinib and everolimus (a small molecule mTOR inhibitor)." (PMID 35945463, 2022). "Ran Marciano, Manu Prasad and colleagues firstly found that EVP4593 inhibited the mTOR pathway in tumor cells growing under glucose starvation but not under normal conditions." (PMID 36555369, 2022). "Additionally, our data reveal that tumor-derived redHMGB1 serves as the priming signal to be sensed by TLR4 and initiate the mTOR/Bcl6-driven program for SMMs development." (PMID 36542153, 2022). "Growth of AMLs was noted after discontinuation of treatment, indicating that mTOR inhibition results in tumor cells being in a quiescent phase as opposed to these cells being eliminated." (PMID 36421797, 2022). "Moreover, LDL encapsulated doxorubicin nanoparticles endocytosis to tumor cell and the results revealed apoptosis by blocking AKT/mTOR signaling pathway." (PMID 36029014, 2022). "PD-L1 knockdown and antibody blockade diminish glucose metabolism and Akt/mTOR signaling in tumor cells without affecting proliferation in vitro or tumor growth in RAG-/- mice." (PMID 36713558, 2022). "By annotating them to relevant biological processes, we noticed significant enrichments in signaling pathways involving mTOR, WNT, Notch, C-myc and hypoxia, which might contribute to the maintenance of stemness and promote tumor progression." (PMID 36127710, 2022). "Finally, overexpression of TPI1 increased expression of N-cadherin, vimentin, LDHA, p-mTOR, and CDCA5, whereas reduced E-cadherin in tumor tissues as demonstrated by WB." (PMID 35509067, 2022).
tumor (continued). "Collectively our results suggested that EGFR, MAP2K1, mTOR, TEAD1, and YAP1 could mediate invasive tumor phenotypes and produce worse prognoses via mechanisms involving both the T-cell exclusion and dysfunctional phenotypes." (PMID 35655775, 2022). "Ten uLMS patient-derived xenograft (PDX) models were successfully generated by Cuppens and associates more recently, five of which were used in a subsequent study to show the benefit of inhibiting mTOR and PI3K signalling in uLMS (4/5 PDX models showed reduction/stabilisation of tumour growth)." (PMID 35326717, 2022). "All hallmarks are context-dependently constituted by the tumor tissue and as such it is not surprising that pre-clinical data on mTOR inhibitors are contradictory." (PMID 35814409, 2022). "Recently, a study focused on the mechanisms other than COX-2 found that celecoxib’s anti-tumor effect on HCC might also involve partner of NOB1 (PNO1) and AKT/rapamycin (mTOR) signaling pathway." (PMID 36713494, 2022). "Researchers found that deguelin could inhibit the proliferation, invasion, metastasis, and autophagy of tumor cells by regulating many signal pathways (e.g., EGFR/IGF1R-Akt, MAPK, and mTOR)." (PMID 35637651, 2022). "Hence, we evaluated the potential role of EGFR, MAP2K1, mTOR, and YAP1 in promoting the infiltration of tumor immune cells within the TME." (PMID 35655775, 2022). "Importantly, pharmacological inhibition of mTOR or MEK lowered the abundance of PCNA, a marker of tumor cell proliferation, and subsequently suppressed cell growth and tumorigenesis in mouse model." (PMID 35437691, 2022). "Based on this, this study would aim to assess the anti-tumor activity of Nigrosporins B for various human tumor cells and focus on the process of PCD characterized by apoptosis and autophagy and the signaling pathway of PI3K/AKT/mTOR to deeply clarify the molecular mechanisms." (PMID 35458629, 2022). "As the PI3K/Akt signaling cascade is the main upstream activator of mTOR, which stimulates tumor angiogenesis, we therefore sought to determine whether visfatin mediates PI3K/Akt/mTOR signaling." (PMID 36359873, 2022). "Furthermore, Hallmark pathway analysis also confirmed that Fibro_2 cells had more relevance with the pathways that sustain tumor growth, including angiogenesis, epithelial-mesenchymal transition (EMT), hypoxia, and PI3K/AKT/mTOR signaling." (PMID 35935940, 2022). "Indeed, there is crosstalk between the two pathways, whereby ERα stimulates the PI3K/AKT/mTOR pathway, favoring migration and tumor invasion, and the PI3K/AKT/mTOR pathway activates the expression of ERα." (PMID 35053485, 2022). "The mTOR inhibitors Everolimus and Temsirolimus have been approved by the FDA, EMA and PMDA for use in some indications, and clinical trials of these and other mTOR inhibitors as well as inhibitors of PI3K and Akt are currently underway in multiple tumor types." (PMID 36077638, 2022). "Cell experiments suggest that KRT17 knockout could inhibit the proliferation and migration of GC cells, which may be achieved through the Akt/mTOR signalling pathway, and animal experiments also confirmed that KRT17 knockout could inhibit tumour growth." (PMID 35281081, 2022). "Additional evidence indicated that VEGF stimulation could activate mTOR signaling, and synchronous inhibition of the mTOR and VEGF axis impedes tumor growth and metastasis." (PMID 36106120, 2022). "Indeed, UGCG mRNA expression and GlcCer levels are increased in the livers of mice with mechanistic target of rapamycin (mTOR)-activated HCC tumors, and UGCG inhibition reduced proliferation of hepatocytes, tumor burden, and markers of liver damage." (PMID 35562868, 2022). "Despite the overall immunosuppressive role of Rapamycin, mTOR inhibition with Rapalogs has been shown to favor the expansion of CD8+ memory T cells and to have a synergistic effect with different types of immunotherapies in some preclinical tumor models." (PMID 36077374, 2022).
tumor (continued). "In summary, tan IIA inhibits the mTOR pathway through different mechanisms and increases the expression of autophagy-related proteins, such as LC3-II and Beclin 1, thereby inducing autophagy in tumor cells." (PMID 36172186, 2022). "In addition, in many studies related to autophagy and apoptosis in tumour cells, AEG-1 has been reported to be closely related to the PI3K/AKT/mTOR pathway." (PMID 35794136, 2022). "Meanwhile, some scientists have proposed that the anti-tumor mechanism of Tetrastigma hemsleyanum may include calcium signaling pathway, PI3K/AKT/mTOR signaling pathway and CDK6 and MET genes." (PMID 36389762, 2022). "In addition to their direct effect on tumors, PI3K/AKT/mTOR and MAPK/MEK/ERK inhibitors have been shown to modulate the tumor microenvironment, increase immunogenicity, and thus potentially facilitate increased sensitivity to immunotherapy." (PMID 35806358, 2022). "However, thereafter the tumor started to grow over the next weeks, indicating the development of resistance against the AKT/mTOR inhibitor treatment." (PMID 35454789, 2022). "mTOR has been evaluated as a drug target in UM: the combinations of the rapamycin analog mTORC1 inhibitor everolimus with either PI3K or PKC inhibitors have been shown to inhibit the growth of UM cell lines and reduce tumor volume in PDX models." (PMID 35804957, 2022). "The release of BEZ235 from H-APBC in acid microenvironment could mitigate PI3K/mTOR signal and resist HIF-1α-dependent tumor hypoxia adaptation." (PMID 35413842, 2022). "Overexpression of YTHDF2 positively activates the mTOR/AKT pathway and regulates the progression of EMT which may act as a tumor promoter to induce LUSC cell proliferation and invasion." (PMID 34996459, 2022). "Dual PI3K/mTOR inhibitors such as dactolisib (BEZ235), apitolisib (GDC-0980), gedatolisib (PF-05212384), bimiralisib (PQR309), paxalisib (GDC-0084), and voxtalisib (SAR245409, XL765) have shown substantial anticancer efficacy in various tumor xenografts." (PMID 35402264, 2022). "In addition, based on IHC, expression levels of CDCA5, Ki67, p-mTOR, and LDHA were higher in tumor tissue generated by TPI1 overexpression cells than vector control; E-cadherin was lower in these tumors." (PMID 35509067, 2022). "Similarly, overexpression of miR-495-3p is sufficient to reverse the multidrug resistant-cell to four chemotherapeutics and suppress the GC tumor growth, as miR-495-3p attenuates the process of autophagy via binding to GRP78 and thus activating mTOR." (PMID 36353541, 2022). "CRG cluster A, from a lack of an immune cell presence, had more of an immune-desert phenotype and was enriched in a variety of tumor signaling pathways, including the TGF- signaling pathway, adhesion, phosphoinositide metabolic pathway, and mTOR signaling pathway." (PMID 35979353, 2022). "There is extensive information about the role of SPOCK1 in the tumour extracellular matrix (ECM) dynamic homoeostasis process, which activates many molecular signalling pathways (such as EMT process, Wnt/β-catenin, PI3K/Akt and mTOR/S6K signalling pathways)." (PMID 35046388, 2022). "miR-615-5p was previously characterized by our group as a tumor suppressor and shown to target mTOR, but to our knowledge, this was never investigated before in fatty liver." (PMID 36203751, 2022). "Current researchers showed that activation of the PI3K/AKT/mTOR pathway could facilitate the process of EMT, thus increasing the metastatic ability of tumor cells." (PMID 35812733, 2022). "Omega-3 PUFAs modulate inflammation even through enhanced expression of DNA methyltransferases (DNMTs) and increased LKB1 tumor suppressor gene expression, in turn stimulating LKB1 activity with a consequent inhibition of glycolytic enzymes and targeting rapamycin (mTOR) signaling." (PMID 35565885, 2022).
tumor (continued). "Blocking mTOR activity by rapamycin can promote memory cell precursors, especially the newly differentiated memory CD8+T cells equipped with more superior anti-tumor activity than IL-2-inducing effector T cells." (PMID 36200045, 2022). "The apoptosis rates of tumor cells were significantly higher in LPS+ mTOR inhibitor+matrine than that in other groups, indicating that CTL induced by LPS+mTOR inhibitor +Matrine group had the strongest killing ability in vivo, which was consistent with the results in vitro." (PMID 35400284, 2022). "The TBK1-dependent mTOR signaling activation in K-RAS/N-RAS-activated tumor cells suggests that TBK1-mTOR and MEK-ERK constitute parallel survival and proliferative signaling pathways in such tumor cells." (PMID 35395857, 2022). "Further understanding with regard to the role of the mTOR pathway in canine OSCC may provide an improved insight of oral tumorigenesis and may open up new treatment possibilities for these tumours." (PMID 35883491, 2022). "During endoplasmic reticulum stress, low concentrations of EGCG lead to autophagy-dependent survival of tumor cells by balancing the mTOR-AMPK pathway, upregulation of downregulated mTOR, and downregulation of upregulated AMPK during autophagy, enhancing cell viability." (PMID 36232338, 2022). "In the future, the developed genetic synthetic circuit may aid in tumor suppression by increasing miR-520c-3p expression in a controllable way, which will then target and block the PI3K/AKT/mTOR signaling pathway." (PMID 35634241, 2022). "In particular, we demonstrated how ANGPTL4 regulates the metabolism of BCAAs, thereby regulating tumor progression of OS through the activation of mTOR signaling pathway, but we do not know exactly how various receptors are involved." (PMID 35461343, 2022). "Furthermore, blockage of ATM, MAPK, and mTOR signaling pathways with inhibitors also prevented citrate‐induced overexpression of ACAT1/2 and cPLA2α for LD formation in MCF7 and HCT116 tumor cells." (PMID 34747157, 2022). "Compared with previous studies, this study further investigated A–S, Astragalus, and scorpion, which might inhibit tumor development by activating autophagy and inhibiting the PI3K/AKT/mTOR pathway based on network pharmacology." (PMID 35847007, 2022). "Gene Ontology (GO) and Kyoto Encyclopedia of Genes and Genomes (KEGG) analysis of SLC25A13 coexpressed genes showed that these genes are enriched in ATPase activity, cell cycle, mTOR, and VEGFA-VEGFR2 signaling pathways, which were relevant to tumor development and angiogenesis." (PMID 35607442, 2022). "Importantly, key oncogenic signalling pathways, including ERK1/2, mTOR, p38, MSK, STAT5, STAT3 and PDGF, were induced in CAFs and less so in the mesothelial cells from the same tumour." (PMID 36293328, 2022). "Tumor proliferation requires increased adenosine triphosphate, activates AMPK, and inhibits mTOR." (PMID 36105371, 2022). "In line with this, KD of ADAM9 in HCT116 cells drastically reduced phospho-S6K, a signature mTOR target that facilitates tumor invasion including CRC invasion, without affecting total S6K levels." (PMID 35780836, 2022). "PTEN can regulate the tumor cells’ proliferation via the mTOR pathway, and 30–60% EC exhibits a lack of PTEN." (PMID 35205261, 2022). "Regulation of T cells via mitochondrial activation ETC and then glycolysis promotion through mTOR/AKT signaling could activate depleted T cells, enhance anti-tumor immune response and impair tumor growth." (PMID 35938036, 2022).